FAM236C (family with sequence similarity 236 member C)
Tractability: No criterion of Open Targets' tractability assessment is met for any kind of drug.
Gene: Protein-coding gene on chromosome X (72,912,615 to 72,913,401, forward strand). Ensembl gene ENSG00000283594.
Homologues: Orthologues: mouse Fam236e (37% identical), rat Fam236d (37% identical), mouse Fam236f (35% identical). Paralogues in human: FAM236D (100% identical), FAM236A (91% identical), FAM236B (91% identical).